KISS1R (KISS1 receptor)
Diseases named in the same sentence as KISS1R in open-access papers (continued):
Sharing a sentence is not in itself a finding about the gene and the disease.
adrenocortical tumor (1 paper, 2017). "In HFA cells, kisspeptin treatment resulted in a significant decrease in Kiss1R mRNA expression in adrenocortical tumor (H295R) and second-trimester HFA cells." (PMID 28911133, 2017).
asthma (1 paper, 2023). "A gene of interest in the lung is kisspeptin (Kiss1) and its receptor (Kiss1r), which have been shown to abate proliferation of ASM cells in vitro with reduced expression in ASM cells from asthma subjects compared with healthy subjects." (PMID 37732890, 2023).
choriocarcinoma (1 paper, 2022). An aggressive malignant tumor arising from trophoblastic cells. "Additionally, low KISS1/KISS1R expression was described in the highly invasive trophoblast cells of choriocarcinoma, while high KISS1/KISS1R expression was reported in the non-invasive cells of benign molar pregnancies." (PMID 37538930, 2022).
chronic kidney disease (1 paper, 2024). Impairment of the renal function secondary to chronic kidney damage persisting for three or more months. "Kisspeptins (KPs) and their receptor, KISS1R, have emerged as potential players in the pathogenesis of chronic kidney disease (CKD) as well as age-related pathologies of other organ systems." (PMID 37987885, 2024).
cleft lip (1 paper, 2015). Congenital defect in the upper lip where the maxillary prominence fails to merge with the merged medial nasal prominences. "One novel heterozygous missense mutation in KISS1R, (NM_032551): c.587C>A (p.P196H), was identified in an 18-year-old KS male with cleft lip and dental agenesis who developed sperm after being treated with gonadotropin." (PMID 26199944, 2015). "One heterozygous missense mutation in KISS1R which was reported previously, (NM_032551): c.587C>A (p.P196H), was identified in an 18-year-old KS male with cleft lip and dental agenesis." (PMID 26199944, 2015).
colorectal cancer (1 paper, 2018). A primary or metastatic malignant neoplasm that affects the colon or rectum. "Interestingly, in cancers such as pancreatic, ovarian, and colorectal cancer, a new facet in the relationship between KISS1/KISS1R and these cancers was uncovered." (PMID 30123188, 2018).
congenital hypogonadotropic hypogonadism (1 paper, 2013). Congenital hypogonadotropic hypogonadism (CHH) is a rare disorder of sexual maturation characterized by gonadotropin (Gn) deficiency with low sex steroid levels associated with low levels of follicle stimulating hormone (FSH) and luteinizing hormone (LH). "KISS1R mutations have been reported in few patients with normosmic congenital hypogonadotropic hypogonadism (nCHH) (OMIM #146110)." (PMID 23349759, 2013).
Delayed puberty (1 paper, 2019). Passing the age when puberty normally occurs with no physical or hormonal signs of the onset of puberty. "The role of KNDY in humans is highlighted from the observations that loss-of-function mutations in the genes encoding for kisspeptin (KISS1), kisspeptin receptor (KISS1R), NKB (TAC3), or NKB receptor (TACR3) are associated with delayed puberty and hypogonadism." (PMID 31920956, 2019).
fetal growth restriction (1 paper, 2022). A fetus that does not grow beyond the 10th percentile of conventionally accepted weight for gestational age. "Maternal hypothyroidism is associated with fetal growth restriction, placental dysfunction, and reduced kisspeptin/Kiss1R at the maternal-fetal interface." (PMID 35966095, 2022).
hepatocellular carcinoma (1 paper, 2023). A malignant tumor that arises from hepatocytes. "Furthermore, Ikeguchi and coworkers reported increased KISS1R expression in hepatocellular carcinoma tissues compared to normal liver tissues." (PMID 38256878, 2023).
invasive ductal carcinoma (1 paper, 2018). "Using immunohistochemistry, studies have shown that KISS1 and KISS1R is localized within the ductal carcinoma in situ and in invasive ductal carcinoma, and that there was higher cytoplasmic staining in tumors as well as surrounding cells, compared to normal tissue." (PMID 30123188, 2018). "We found localization of KISS1 and KISS1R in invasive ductal carcinoma tumors using immunostaining." (PMID 30123188, 2018).
liver cancer (1 paper, 2018). An epithelial or non-epithelial malignant neoplasm that arises from the liver. "Since then, it has become apparent that KISS1, KPs, and KISS1R regulate the development and progression of several cancers but interestingly, while these molecules act as suppressors of tumorigenesis and metastasis in many cancers, in breast and liver cancer they function as promoters." (PMID 30123188, 2018).
liver disease (1 paper, 2022). "Overall, the data suggest that the KISS1/KISS1R signaling pathway is enhanced in patients with liver disease, possibly as an adaptive mechanism in response to injury of the liver." (PMID 35349482, 2022).
male infertility (1 paper, 2024). The inability of the male to effect fertilization of an ovum after a specified period of unprotected intercourse. "Five of these genes were characterized as male infertility‐related genes, including Polo‐like kinase 4 (PLK4), AGTPBP1, KISS1 receptor, Meiosis Expressed Gene 1 (MEIG1), and Piwi Like RNA‐Mediated Gene Silencing 2 (PIWIL2)." (PMID 37937809, 2024).
nasopharyngeal carcinoma (1 paper, 2021). A carcinoma arising from the nasopharyngeal epithelium. "The western blot protein expression analysis revealed that KISS1 and KISS1R were also lowly expressed in poorly differentiated nasopharyngeal carcinoma cells compared with well differentiated nasopharyngeal carcinoma cells." (PMID 35117986, 2021). "At the same time, the expression levels of KISS1 and KISS1R are positively correlated with the differentiation degree of cells in the nasopharyngeal carcinoma cell line, indicated by RT-PCR and western blotting." (PMID 35117986, 2021). "However, whether the KISS1 gene and its receptor KISS1R gene are involved in the regulation and how to regulate the proliferation mechanism of nasopharyngeal carcinoma is unclear." (PMID 35117986, 2021). "The RT-PCR analysis revealed that compared with well differentiated nasopharyngeal carcinoma cells, such as CNE-1 cells and HK-1 cells, the mRNA of KISS1 and KISS1R were lowly expressed in poorly differentiated nasopharyngeal carcinoma cells, such as HNE1 cells and 5-8F cells." (PMID 35117986, 2021). "Taken together, the current study illustrates a molecular and signal pathway basis for better understanding of how KISS1/KISS1R alters LKB1 activation and thereby activates the AMPK signaling pathway, ultimately inhibits the proliferation of nasopharyngeal carcinoma." (PMID 35117986, 2021). "Due to the lack of studies evaluating the role of KISS1 and KISS1R in the proliferation of nasopharyngeal carcinoma cells, we have tried to assess its role and molecular mechanism in nasopharyngeal carcinoma progression." (PMID 35117986, 2021).
osteosarcoma (1 paper, 2019). A usually aggressive malignant bone-forming mesenchymal neoplasm, predominantly affecting adolescents and young adults. "Kiss1r (gpr54) expression was observed in all osteosarcoma cells tested, primary samples, and normal OPCs." (PMID 30777054, 2019).
placenta previa (1 paper, 2024). "Furthermore, the KISS1 receptor gene expression level increased 170-fold in the placenta previa group." (PMID 38996103, 2024).
preeclampsia (1 paper, 2012). Preeclampsia is a hypertensive disorder of pregnancy that is characterized by new-onset hypertension with proteinuria presenting after 20 weeks of gestation, and depending on mild or severe forms may initially present with severe headache, visual disturbances, and hyperreflexia. "They found reduced expression of KiSS-1 and increased expression of KiSS1R in preeclampsia compared with control term pregnancy at both the protein and mRNA levels." (PMID 23145030, 2012).
renal carcinoma (1 paper, 2019). A carcinoma arising from the epithelium of the renal parenchyma or the renal pelvis. "In human renal carcinoma cell (RCC) 786-0, honokiol significantly upregulated the expression of metastasis suppressor gene (KISS-1), genes encoding TIMP metalloproteinase inhibitor 4 (TIMP4), and KISS-1 receptor (KISS-1R)." (PMID 31877856, 2019).
sarcoma (1 paper, 2017). A usually aggressive malignant neoplasm of the soft tissue or bone. "However, the possible association among KISS1R and sarcoma has not been reported." (PMID 28404969, 2017).
squamous cell carcinoma (1 paper, 2021). A carcinoma arising from squamous epithelial cells. "First, we found that Kiss1 and Kiss1R were lowly expressed in squamous cell carcinoma tissues and highly expressed in nonkeratinizing squamous cell carcinoma tissues by immunohistochemistry." (PMID 35117986, 2021). "In this study, we identified that the expression of KISS1 and its receptor KISS1R in squamous cell carcinoma tissues was lower than that of nonkeratinizing squamous cell carcinoma tissues." (PMID 35117986, 2021). "This work showed that KISS1 and KISS1R were lowly expressed in squamous cell carcinoma tissues and highly expressed in nonkeratinizing squamous cell carcinoma tissues by immunohistochemistry." (PMID 35117986, 2021).
tumor (45 papers, 2007 to 2026). "The tumor-suppressive role of the KISS1R was mainly linked to the inhibition of tumor invasion via the suppression of nuclear factor kappa-B (NF-κB) activity and expression of MMP-9 and by inhibiting mitogen-activated protein kinase (MAPK) and ERK pathways." (PMID 37640761, 2023). "Although the loss of KISS1 and KISS1R expression has been associated with tumor progression and poor prognosis in various cancers, the mechanism underlying this phenomenon is still unclear." (PMID 35117986, 2021). "However, in some cancer types, the KISS1/KISS1R pathway has been associated with tumor progression and increased metastatic ability." (PMID 37640761, 2023). "The application of the KISS1R as a target in the clinical setting therefore appears to depend on the type of primary tumour and KISS1R expression profile." (PMID 39775975, 2025). "As shown for other [68Ga]Ga‐DOTA peptides, lutetium‐177 labelling would potentially serve as a therapeutic but also for surgical debulking in primary tumours where KISS1R has a tumour suppression effect." (PMID 39775975, 2025). "The secreted kisspeptin peptides act in a paracrine or autocrine fashion, influencing surrounding stromal or immune cells even when tumor cells themselves lack KiSS-1R, generating growth-inhibitory microenvironments." (PMID 41567980, 2025). "KP‐10 together with KISS1R has been observed to display a stimulatory or inhibitory role in tumours depending on the type of cancer." (PMID 39775975, 2025). "In some tumour types, the KISS1R/KISS1 pathway is upregulated in the primary tumour and serves as a tumorigenesis and metastasis suppressor." (PMID 39775975, 2025). "They proposed that overexpression of the KISS1R gene leads to significantly higher glutamate levels in primary tumours than in control tumours." (PMID 38187259, 2024). "KISS1R, also known as GPR54, is a Gα–q/11–coupled GPCR, was found to be overexpressed in TNBC, and is associated with tumor invasion and migration." (PMID 37174125, 2023). "In order to identify appropriated tumor cell lines expressing KISS1R for in vitro binding studies, we examined different human tumor cell lines of various tumor types both by immunofluorescence (IF) and Western blot (WB)." (PMID 38256878, 2023). "On the one hand, addressing KISS1R should open up the possibility of the prognosis of progression in tumor patients." (PMID 38256878, 2023). "In [68Ga]KISS1-54-PET, KISS1R-positive LNCap-tumors were clearly visualized as compared to MDA-MB-231-tumor implant with predominantly intracellular KISS1R expression." (PMID 38256878, 2023). "In particular, deeper investigations aimed at clarifying the role played by the expression of KiSS1 and KiSS1R as well as the contribution of secreted KiSS1 by the tumor are needed." (PMID 37790750, 2023). "Nevertheless, to our knowledge, we radiolabeled, for the first time, a KISS1R radioligand for PET-imaging of KISS1R-expressing tumors and successfully evaluated it in cell culture and an in vivo experiment in a tumor xenograft." (PMID 38256878, 2023). "The preclinical evaluation in several tumor cell lines and in tumor-bearing mice demonstrates a specific accumulation of the new radiotracer in KISS1R-expressing tumor cells in vitro and in vivo." (PMID 38256878, 2023). "Examples include alpha-bisabolol, an effective inhibitor of tumor aggressiveness in PC, whose cancer-suppressive effects were previously proved relevant to the activation of KISS-1R, giving rise to new ideas for the clinical treatment of PC." (PMID 35875143, 2022). "Our future work will evaluate the role of c-Myc in stimulating KISS1R-induced tumor growth and metastasis in vivo." (PMID 32034133, 2020). "Recently, we reported that KISS1/KISS1R expression are upregulated in TNBC patient tumor biopsies compared with healthy breast tissue and that KISS1R signaling induces a drug-resistant phenotype in TNBC25." (PMID 32034133, 2020).
tumor (continued). "Another new finding is that in addition to regulating tumor growth and metastasis in vivo, KISS1R regulates metabolic changes in tumors." (PMID 32034133, 2020). "KISS1/KISS1R expression are upregulated in TNBC patient tumor biopsies and high KISS1 expression has been shown to correlate with increase in lymph node metastasis." (PMID 32034133, 2020). "Stable knockdown of KISS1R reduced primary tumor volume and the capacity of tumor cells to metastasize and colonize the lungs compared with scrambled shRNA controls." (PMID 32034133, 2020). "The findings reported here demonstrate for the first time that human KISS1R promotes TNBC tumor growth and metastasis using preclinical xenograft models." (PMID 32034133, 2020). "Gpr54/Kiss1R expression was observed in normal osteoblast cells at levels significantly lower than what was found in tumor lines." (PMID 30777054, 2019). "Consistently, in pancreatic and ovarian cancer, KISS1/KISS1R was found to be upregulated in initial phases of cancer development, thus acting as a tumor suppressor." (PMID 31336647, 2019). "Since the seminal discovery that KISS1 regulates metastasis of melanoma cells, a large and growing body of studies has described roles for KISS1 and KISS1R mRNA and protein in regulating tumor growth and metastasis." (PMID 30123188, 2018). "Recent papers attribute to KiSS-1/KiSS-1R complex a diverse function from that observed in other tumor types." (PMID 29760678, 2018). "In this review, we focused on multiple functions exerted by the KPs/KiSS-1R system in regulating tumor progression." (PMID 29760678, 2018). "Although the anti-metastatic role has not been studies extensively as compared to the reproductive function, nevertheless a large body of literature documented the involvement of the KiSS-1/KiSS-1R system in supporting tumor progression." (PMID 29760678, 2018). "Decreased expression of KiSS-1R seems to attenuate signaling of the KiSS-1/KiSS-1R system, possibly leading to tumor growth." (PMID 29760678, 2018). "Collectively, these results indicate that KISS1R signaling promotes tumor chemoresistance and pharmacological inhibition of KISS1R re-sensitizes cancer cells to doxorubicin, enabling them to undergo apoptosis." (PMID 28422142, 2017). "IHC for KISS1R demonstrated a trend of protein overexpression in tumor samples corresponding to stages I, II, III, and metastasis, however only stage I and stage III results were considered to be statistically significant based upon H scores (p≤0.05)." (PMID 24979721, 2014). "Of these, we further establish a role for CDH13 in tumor angiogenesis, as well as a pro-migratory role for four novel factors including KISS1R, KSR1, CAMK1, and SSPN in ccRCC." (PMID 24979721, 2014). "Here we showed that KISS1R is expressed in hypoxic areas and endothelial cells of tumor blood vessels, pointing to a putative role in angiogenesis." (PMID 19536297, 2009). "GPR54, or KiSS-1R (Kisspeptin receptor), is key in puberty initiation and tumor metastasis prevention, but its role on hair follicles remains unclear." (PMID 39587329, 2024). "The NODAGA-KISS1-54 peptide was labeled by Gallium-68, and the stability of the resulting [68Ga]KISS1-54 evaluated in injection solution and human serum, followed by an examination in different KISS1R-expressing tumor cell lines, including HepG2, HeLa, MDA-MB-231, MCF7, LNCap, SK-BR-3, and HCT116." (PMID 38256878, 2023). "On the other hand, KISS1R-positive tumor patients could be selected for subsequent individualized radionuclide therapy with the corresponding α/β−-emitting KISS1R radioligands." (PMID 38256878, 2023). "Thus, further [68Ga]KISS1-54 circulation was highly reduced, resulting in the relatively low absolute tracer accumulation in the KISS1R-positive LNCap tumor." (PMID 38256878, 2023).